ENSG00000255641 (novel protein)
Gene: Protein-coding gene on chromosome 12 (10,412,312 to 10,436,001, reverse strand). Ensembl gene ENSG00000255641.
Genetic constraint (gnomAD): Loss-of-function variants: 11 observed, 19.63 expected, observed/expected ratio (o/e) 0.56, 90% interval 0.35 to 0.93. Missense variants: 141 observed, 204.84 expected, observed/expected ratio (o/e) 0.69, 90% interval 0.6 to 0.79. Synonymous variants: 55 observed, 61.21 expected, observed/expected ratio (o/e) 0.9, 90% interval 0.72 to 1.12.